IL33 (interleukin 33)
Diseases named in the same sentence as IL33 in open-access papers (continued):
Sharing a sentence is not in itself a finding about the gene and the disease.
atherosclerosis (continued). "IL‐33 plays an anti‐inflammatory role in atherosclerosis, cutaneous wound healing, intestinal, and adipose tissue inflammation via expansion of Tregs." (PMID 33034128, 2020). "Because of the complex actions that IL-33 plays in tissue injury and inflammation, it has been involved in the pathogenesis of several diseases (e.g., allergy, autoimmune diseases, cancer, atherosclerosis, and diabetes)." (PMID 30813357, 2019). "Due to the effect of IL-33 on Th2-type immune response, IL-33 exhibits a protective role in the pathogenesis of atherosclerosis." (PMID 30761089, 2019). "IL-33 also reduces the formation of foam cells and the development of atherosclerosis by blunting the Th1 and M1 immune responses, while sST2 has deleterious effects by sequestering IL-33." (PMID 31235844, 2019). "Recent studies have shown that IL-33 prevents the development of parasitic infection, allogeneic allograft rejection and atherosclerosis." (PMID 30863362, 2019). "Due to the fact that the peritoneal cavity is the main residence of B1 cells we decided to transfer IL-7, IL-33-expanded ILC2s intraperitoneally to apoE−/− mice and study the induced immunological response as well as their effect on atherosclerosis." (PMID 31823769, 2019). "sST2 decreases the tissue availability of IL-33 and thus blocks the anticardiac hypertrophy and protective effects against atherosclerosis by binding to it." (PMID 31235844, 2019). "This review summarizes the regulation of IL-33 on different immune cells in lipid metabolism, which will help to understand the pathology of abnormal lipid metabolic diseases, such as atherosclerosis and type 2 diabetes." (PMID 30761089, 2019). "IL-33 regulates the switch of T cells to Th1 or Th2 cells and the secretion of relative cytokines in atherosclerosis to reduce the formation of atherosclerosis plaque." (PMID 31547872, 2019). "It has been confirmed that serum IL‐33 was involved in various diseases including asthma, obesity, atherosclerosis, and Alzheimer disease." (PMID 31397082, 2019). "IL-33 can have protective properties in atherosclerosis development and blood concentrations of sST2 are markedly increased in cardiac diseases and metabolic syndrome." (PMID 29988422, 2018). "The present study provides a new insight into the role of IL-33-induced IL-8 expression in the pathophysiology of atherosclerosis and vascular inflammation." (PMID 29373608, 2018). "IL-33 is a cytokine with an important role in the inflammatory process and in the pathogenesis of atherosclerosis." (PMID 28045954, 2017). "IL-33 signaling via ST2 inhibits the development of atherosclerosis, and therefore, sST2 is thought to be proatherogenic." (PMID 28553430, 2017). "On the contrary, in the development of atherosclerosis, IL-33 markedly increased the levels of IL-4, IL-5, and IL-13, and decreased the level of IFN-γ." (PMID 28423665, 2017). "In spite of the important role of IL-33 in the development of atherosclerosis, too few studies have explored the possible role of the gene that encodes this cytokine in the genetic susceptibility to coronary artery disease." (PMID 28045954, 2017). "al. showed exogenous administration of IL-33 shifts TH1 to TH2 response via the ST2/IL-33 axis which alleviated inflammation in a mouse model of atherosclerosis." (PMID 26735493, 2016). "We elected to focus on IL‐18, IL‐33, and TNF, because these cytokines have been implicated in the pathology of both atherosclerosis and RA." (PMID 26749303, 2016). "IL-33 induced Th2 cytokines and Th2 antibodies in serum and lymph node cells of ApoE (−/−) mice, which was a classic murine model of atherosclerosis." (PMID 27172901, 2016). "In apoE knockout mice on a high-fat diet, IL-33 has been shown to reduce atherosclerosis development." (PMID 26504600, 2015). "IL-33 has shown a protective role in the ApoE−/− experimental atherosclerosis mice model, increasing serum levels of Th2-type cytokines, and enriching ST2+CD4+ T cells in lymph nodes." (PMID 26082774, 2015).
atherosclerosis (continued). "Previous studies on murine models have shown that IL-33 reduces the development of atherosclerosis through the induction of anti-oxidized LDL-C antibodies." (PMID 24886535, 2014). "Previous studies using in vivo disease models have shown that IL-33 exacerbates allergic inflammation 18 but confers resistance to parasite infection 19 and attenuates atherosclerosis 20 through inducing type 2 immune responses." (PMID 25116404, 2014). "Experimental studies suggest a possible implication of IL-33 in development and progression of atherosclerosis." (PMID 24725541, 2014). "In accordance to these data, a recent study has shown that sST2 administration exacerbates atherosclerosis development in a mouse model of atherosclerosis by suppressing IL-33 function." (PMID 24265755, 2013). "IL-33 stimulates conventional Th2 cells to release IL-4, IL-5, and IL-13 and IL-33-driven Th2 cells profoundly inhibit atherosclerosis." (PMID 23653627, 2013). "Recently, studies in rodents indicated that IL-33 is expressed in the heart, by cardiac fibroblasts after mechanical stress and by endothelial cells during atherosclerosis." (PMID 18836528, 2008). "Moreover, the protective effects against atherosclerosis of IL-33 were hindered by combining it with a neutralizing anti-IL-5 antibody, indicating that the assistance provided by IL-33 in vivo is possibly mediated through an IL-5-driven response." (PMID 39844544, 2025). "The dysregulated expression of IL-33 suggests that it might be somehow involved in the pathogenesis of atherosclerosis." (PMID 39194749, 2024). "IL-33 is a newly discovered cytokine that belongs to the IL-1 cytokine family and has been demonstrated to play interesting roles in various cardiovascular disease processes, including myocardial infarction, atherosclerosis, and cardiac fibrosis." (PMID 37509127, 2023). "Interleukin (IL-33) and the ST2 receptor are implicated in the pathogenesis of atherosclerosis." (PMID 37240352, 2023). "Although described in a murine atherosclerosis model as an atheroprotective cytokine, extracellular IL-33 induces proinflammatory, prothrombotic, and proangiogenic activation of human endothelial cells and stimulates the release of procoagulant microvesicles from human monocytes." (PMID 37240352, 2023). "ST2 and IL-33 are expressed in endothelial cells and may play an important role in vascular biology and the development of hypertension and atherosclerosis." (PMID 37371771, 2023). "The IL-33/ST2 axis is involved in the pathogenesis of atherosclerosis." (PMID 37240352, 2023). "IL-33 prevents the formation of atherosclerotic plaques, reducing atherosclerosis." (PMID 36291105, 2022). "However, there were studies that demonstrated the protective role of IL-33 in atherosclerosis, where the development of atherosclerosis was significantly reduced in ApoE−/− mice administered with IL-33 through Th1-to-Th2 switching." (PMID 36552551, 2022). "Investigations of IL-33 in atherosclerosis revealed that this cytokine stimulates the expression of the endothelial adhesion molecules VCAM1, ICAM1 and E-selectin as well as the expression of CCL2 in HUVECs in a concentration-dependent manner resulting in increased leukocyte adhesion." (PMID 35600479, 2022). "Immuno-modulatory properties of IL-33 have been studied previously, and its role in the modulation of inflammatory pathologies of the respiratory system, gastrointestinal tract, and other inflammatory diseases such as atherosclerosis has also been reported." (PMID 33671042, 2021). "IL-17 and IL-33 are potential cytokines and key regulators of inflammatory responses and are reported to play a significant role in cardiovascular diseases such as dilated cardiomyopathy, myocardial ischemia, atherosclerosis, and myocarditis." (PMID 34754275, 2021). "In contrast to those results, the deficiency in IL-33/ST2 signaling did not affect atherosclerosis severity in double knock-out IL-33−/−ApoE−/− and ST2−/−ApoE−/− mice." (PMID 34948083, 2021).
atherosclerosis (continued). "For example, IL-33 treatment of ApoE−/− mice alleviates atherosclerosis." (PMID 33671042, 2021). "One explanation for this discrepancy could be the fact that the systemic administration of IL-33 induces Th2 responses, which might result in a different outcome in the setting of atherosclerosis as compared to physiological amounts of endogenous IL-33." (PMID 34948083, 2021). "While a few reports have shown that IL-33 induced endothelial cell activation and increased angiogenesis and vascular permeability, in contrast, others have demonstrated that treatment with IL-33 reduced experimental atherosclerosis." (PMID 32194407, 2020). "As atherosclerosis is predominantly a Th1-driven process, it may imply that IL-33 might have potential vascular effects." (PMID 31235844, 2019). "IL-1β represents the tip of the iceberg; there are several other potential inflammatory mediators that could be directly targeted to halt atherosclerosis progression, such as by directly targeting the inflammasome, IL-1α, IL-6, IL-18, and IL-33, among others." (PMID 31672136, 2019). "It should be added that in atherosclerosis, IL-33 was protective." (PMID 29988422, 2018). "However, by switching Th1/Th17 to Th2 type immune response, IL-33 can reduce the development of atherosclerosis, graft rejection and EAE, which are mainly mediated by Th1 and Th17 response." (PMID 28423665, 2017). "We hypothesize that the IL-33/ST2 axis may be one of the potential pathways providing the link between atherosclerosis and osteoporosis in PsA patients." (PMID 27554830, 2016). "We hypothesized that IL-33/ST2 axis could be a link between atherosclerosis and compromised bone quality in PsA patients." (PMID 27554830, 2016). "Interestingly, it has been demonstrated that IL-33 is a potent inhibitor of macrophage foam cell formation in vivo and in vitro and attenuates atherosclerosis." (PMID 27579324, 2016). "Nevertheless, the low detection rate could mask the direct correlation between IL-33 and atherosclerosis or compromised bone quality, and limit the utility of blood IL-33 as a biomarker in PsA." (PMID 27554830, 2016). "Administration of excess soluble ST2 has been shown to exacerbate atherosclerosis in mice 3, suggesting that expression of circulating IL‐33 in the local lesion may indeed be protective." (PMID 26749303, 2016). "Through induction of TF in ECs, IL-33 could enhance their thrombotic capacity and thereby might impact on thrombus formation in the setting of atherosclerosis." (PMID 27142573, 2016). "Furthermore, it has been demonstrated that IL-33 treatment attenuated atherosclerosis in ApoE−/− mice and reduced adiposity in ob/ob mice in a ST2 dependent manner." (PMID 27172901, 2016). "IL-33 may play a protective role in the development of atherosclerosis via the induction of IL-5 and ox-LDL antibodies." (PMID 27579324, 2016). "In conclusion, plasma sST2 levels were independently associated with both carotid plaque and compromised cortical vBMD/microstructure in PsA patients, indicating that IL-33/ST2 axis may contribute to both atherosclerosis and osteoporosis." (PMID 27554830, 2016). "Furthermore, lipid metabolism disorder often occurred in gout patients, which caused kidney damage in gout patients, and recent study has shown that IL-33 plays a protective role in atherosclerosis." (PMID 27579324, 2016). "The results described herein show that the deficiency of the endogenous IL‐33/ST2‐axis does not impact the development of atherosclerosis in ApoE‐deficient mice." (PMID 26417439, 2015). "Moreover, a relationship between baseline detectable IL-33 concentrations and the development of severe subclinical atherosclerosis in patients diagnosed with RA has been described." (PMID 26571131, 2015). "In addition, IL-33 has been suggested to play a protective role in the development of atherosclerosis via the induction of IL-5 and ox-LDL antibodies." (PMID 25629516, 2015).
atherosclerosis (continued). "Interestingly, IL-33 has been suggested to play a protective role in the development of atherosclerosis by inducing IL-5 and oxidized LDL specific antibodies." (PMID 25629516, 2015). "Moreover, detectable IL-33 plasma concentrations at the time of disease diagnosis were found to predict the presence of severe subclinical atherosclerosis in the extended follow-up of patients with RA." (PMID 26571131, 2015). "In addition, blockade of OX40L reduced experimental atherosclerosis, induced IL-33 production by antigen presenting cells resulting in an increase of IL-5 and natural IgM specific for oxidized LDL." (PMID 25629516, 2015). "IL-33 (also called IL-1F11) is member of the IL-1 family, which induces Th2-type responses, and has been recognized to inhibit the inflammatory response in atherosclerosis by stimulating a Th1-to-Th2 switch and increasing the number of regulatory T cells." (PMID 26504600, 2015). "Similarly, studies in murine (ApoE-/-) models have reported a protective role for IL-33, when administered systemically, against the development of atherosclerosis and cardiovascular disease." (PMID 24886535, 2014). "For just one example, the ability of IL-33 to promote the alternative activation of macrophages, results in outcomes that go well beyond that of wound repair or parasite control and include a protective effect on atherosclerosis." (PMID 25028340, 2014). "Interestingly, CCN3 was revealed to interact with IL-33, which has been suggested to have protective effects against atherosclerosis." (PMID 24722330, 2014). "Taken together these results indicate that IL-33/ST2 signaling may play a protective role in atherosclerosis." (PMID 21871091, 2011). "Given the evidence from the canakinumab trial, we propose that the reduced plaque burden observed after IL1RAP blockade is at least in part mediated by limiting IL-1 signalling but that IL-33 and IL-36 signalling may also act to aggravate atherosclerosis by promoting chemokine release." (PMID 38563353, 2024). "Therefore, IL-33 is vital in maintaining cardiovascular system homeostasis and may be an essential indicator for predicting potential atherosclerosis." (PMID 36291105, 2022). "The IL-33-mediated inhibition of atherosclerosis-associated genes, like MCP-1 and ICAM-1 (intercellular adhesion molecule 1), was also reported in the macrophages, and this anti-atherogenic action of IL-33 involved various signaling pathways, i.e., p38α, ERK1/2, JNK1/2, PI3Kγ, and NF-κB." (PMID 36552551, 2022). "Interestingly, earlier studies pointed out that IL-33 could attenuate the occurrence and development of atherosclerosis by inducing IL-5 and ox-LDL antibodies." (PMID 33854693, 2021). "Furthermore, in vitro IMs reacted to the alarmin IL-33 with an upregulation of TF via an NF-kB dependent pathway, a pathway probably active also in patients with atherosclerosis as monocyte-derived microvesicles positive for TF were correlated with IL-33 plasma levels." (PMID 30778349, 2019). "Indeed, IL-33 may exert protective effects against atherosclerosis in ApoE-/- mice and prevents adipose tissue inflammation in obese mice." (PMID 30813357, 2019). "IL-33 would be associated with the process of atherogenesis by increasing IL-8 production via the IL-33/ST2 system, and therefore, further studies are needed to determine whether IL-33-induced IL-8 is associated with the pathophysiology of atherosclerosis." (PMID 29373608, 2018). "Therefore, IL-33 could inhibit the development of atherosclerosis in vivo by inducing a phenotypical Th1-to-Th2 switch, as atherosclerosis is considered as a Th1-driven chronic disease of the vasculature." (PMID 27223112, 2016). "Thereby, IL-33 could contribute to the development of a prothrombotic microenvironment favouring thrombus formation at sites of vascular injury and inflammatory activation in blood vessels affected by atherosclerosis." (PMID 27142573, 2016).
atherosclerosis (continued). "IL-33/ST2 axis may be a link between accelerated atherosclerosis and osteoporosis in PsA." (PMID 27554830, 2016). "Consequently, it could be plausible to think that the mutant IL33 rs3939286T allele might influence the development of subclinical atherosclerosis by regulating the expression of IL33 and, at last, by decreasing IL-33 levels." (PMID 26571131, 2015). "However, no study addressed the development of atherosclerosis in atherosclerotic‐prone mice deficient in either IL‐33 or ST2." (PMID 26417439, 2015). "Altogether, this evidence suggests that the IL-33/ST2 axis is involved in the development of atherosclerosis, and proposes that a problem on IL-33 signaling may affect the ability of the organism to respond adequately to an unbalance of the organism homeostasis." (PMID 26082774, 2015). "Taking into account all these considerations, in the present study we aimed to determine, for the first time, whether 6 genetic variants at IL33 and IL1RL1, previously associated with immune-mediated diseases, are involved in the risk of subclinical atherosclerosis in Spanish patients with RA." (PMID 26571131, 2015). "In addition, IL-33 may have dichotomous functions during inflammation, as it has been shown to be protective in a few inflammatory-related conditions, including atherosclerosis and hepatitis." (PMID 23634226, 2013). "Thus, it was hypothesized that IL-33 may have protective effects during atherosclerosis by inducing a Th1-to-Th2 switch of immune responses." (PMID 21871091, 2011). "By competitively binding with IL-33, sST2 can block the IL-33/ST2L signaling pathway and then involve in the entire process of atherosclerosis formation in CAD." (PMID 40295953, 2025). "As a decoy receptor for IL-33, sST2 competitively binds to IL-33, thereby interfering with the IL-33/ST2L signaling pathway and modulating pathological processes such as atherosclerosis and cardiac remodeling." (PMID 40873950, 2025). "Recent studies indicate that IL-33 and ST2L play a defensive role in atherosclerosis and cardiac restructuring." (PMID 39844544, 2025). "This study demonstrates an atherosclerosis-preventive mechanism of ILC2, attenuating saturated fatty acid accumulation by IL-33." (PMID 38674885, 2024). "The present study showed increased IL‐33 and ST2 levels in renal and circulating proteins across multiple rodent models and human DN subjects, including T2D‐related DN and atherosclerosis‐related DN." (PMID 39465143, 2024). "The IL-33/ST2L signaling pathway plays a cardioprotective role, including delaying the onset of atherosclerosis, anti-myocardial fibrosis, reducing myocardial cell death, and improving prognosis." (PMID 38428890, 2024). "Elevated levels of IL-33 and its soluble receptor sST2 were observed in patients suffering from pathologies such as diabetes, obesity, CAD, stroke and atherosclerosis." (PMID 35600479, 2022). "We focus on the contribution of cytokine networks encompassing IL-4, IL-6, IL-9, IL-17A, IL-33 but also IFN-γ and TNF-α to vascular dysfunction in atherosclerosis." (PMID 32194407, 2020). "IL-33/ST2 signaling is a protective pathway in different cardiovascular diseases, and IL-33 induces immune responses during atherosclerosis." (PMID 28881679, 2017). "This is the first study which evaluated the IL-33/ST2 axis, atherosclerosis and bone quality in a single patients’ group." (PMID 27554830, 2016). "IL-33 reduced HFD-induced macrophage foam cell formation and attenuated the development of atherosclerosis." (PMID 27172901, 2016). "In atherosclerosis setting, lymphocytes T-helper seemed to show reduced levels of ST2 receptor and while a dysfunction in IL-33/ST2 axis was also able to dysregulate lymphocytes-Treg which usually reduce the inflammatory burden of systemic atherosclerosis." (PMID 27223112, 2016). "In addition, IL-33 secreted from ILC2 induces Th2 cytokines and ox-LDL antibodies and inhibits atherosclerosis development." (PMID 38674885, 2024).